FLI1 (Fli-1 proto-oncogene, ETS transcription factor)
Diseases named in the same sentence as FLI1 in open-access papers (continued):
Sharing a sentence is not in itself a finding about the gene and the disease.
leukemia (continued). "Our group has used a luciferase-based expression assay to identify antagonists of Fli-1, some of which displayed strong anti-cancer activity in culture and animal models of leukemia." (PMID 28052010, 2017). "Fli-1 expression is induced in various human cancers including breast, melanoma, lymphomas and leukemia." (PMID 28052010, 2017). "As many Rosa26-SB11; T2onc mice with gliomas also have leukemias, it is possible that Fli1 insertions cloned from gliomas actually come from CNS infiltrating leukemia cells." (PMID 25423036, 2014). "As Fli-1 overexpression severely perturbed T cell development after 10–12 weeks in vivo we monitored Fli-1-transplanted mice for leukaemia or lymphoma induction over an extended period." (PMID 23667468, 2013). "The Fli-1 leukaemia phenotype was very similar to the preleukaemic phenotype with reduced CD4+, CD4+8+ and expanded CD8+ cells evident." (PMID 23667468, 2013). "Fli1 (Friend leukemia integration 1 transcription factor) was identified in the mouse genome as a viral integration site common to 2 retroviruses involved in virus-induced leukemias and lymphomas." (PMID 23329308, 2013). "It is also possible that while leukemia suppression activity of anti-FLI1 compounds is robust, inhibition of FLI1 may activate some pro-tumorigenic pathway(s) that counteracts some of its anti-neoplastic function." (PMID 39769192, 2024). "Consequently, FLI-1 expression in acute lymphoblastic lymphoma/leukemia has been evaluated more extensively than in other hematolymphoid neoplasms." (PMID 38280044, 2024). "We therefore examined whether FLI1 function was impaired by Ai treatment, leading to leukemia inhibition." (PMID 39769192, 2024). "DMRs were highly patient-specific, with only 89 genes containing DMRs in all three patients; however, this set included genes involved in leukemia, hematopoiesis, and multipotency, such as FLI1, EGFL7, and TCF15.36–40 We then analyzed the genomic features associated with DMRs across our cohort." (PMID 39553934, 2024). "Interestingly, the level of leukemia suppression by anti-FLI1 inhibitors is slightly less than that seen in mice treated with As-A." (PMID 39769192, 2024). "While FLI1 is known to promote the initiation and progression of leukemias and other cancers, the underlying mechanism is not fully understood." (PMID 38461240, 2024). "Fli1 (Friend leukemia integration 1), a member of the ETS transcription factors family, was first described as a factor implicated in the etiology of virally-induced leukemia, Friend murine leukemia virus-induced erythroleukemia." (PMID 36768203, 2023). "All three Meis1 leukemia models show a strong Meis1 peak at the same position of the Fli1 locus." (PMID 35624144, 2022). "Both FLI1 and ERG have also been implicated in normal hematopoiesis and leukemia formation." (PMID 35624144, 2022). "We further validated Meis1 binding to the mouse Fli1 locus via ChIP-seq in two independent leukemia models, derived from lineage depleted bone marrow cells retrovirally transduced with NUP98-HOXD13/Meis1 (ND13/Meis1) and NUP98-HOXA10 homeodomain/Meis1 (NA10HD/Meis1)." (PMID 35624144, 2022). "Therefore, targeting enhancers of genes involved in leukemia would be one mechanism by which Fli-1 contributes to erythroleukemia." (PMID 33733070, 2021). "For example, professor Ben-David’s group has found that Fli-1 was a proto-oncogene in leukemia, and inhibiting the expression of Fli-1 could inhibit the proliferation of leukemia cells and induce apoptosis." (PMID 32210104, 2020). "These diterpenoids may provide important new tools for the treatment of leukemia and lymphomas driven by overexpression of Fli-1." (PMID 30741932, 2019). "However, we showed that these drugs in part set in motion a Fli-1–miR-145 autoregulatory loop that extinguishes Fli-1 expression and suppresses leukemia." (PMID 30741932, 2019). "Thus, A661 and A665 exhibit anti-leukemic activity against leukemias driven by Fli-1 overexpression." (PMID 30741932, 2019).
leukemia (continued). "The ability of A661 and A665 to block growth of B-cell lymphomas from multiple independent patients as well as leukemogenesis in a preclinical model point to their potential application as drugs for the treatment of leukemias and other cancers driven by Fli-1 overexpression." (PMID 30741932, 2019). "Thus, PKC agonists offer a novel approach to combat Fli-1-induced leukemia, and possibly other cancers,by inducing EMC in part through over-activation of the PKC-MAPK-Fli-1 pathway." (PMID 28052010, 2017). "Fli-1 was initially isolated following retrovirus insertional mutagenesis screens for leukemic initiator genes, and accordingly, inhibition of this transcription factor can suppress leukemia through induction of erythroid differentiation." (PMID 28052010, 2017). "Overall, these data suggest that both activation and inactivation of Fli-1 may have therapeutic benefit for the treatment of leukemia and likely other type of cancers expressing this ETS member." (PMID 28052010, 2017). "Thus, paradoxically, activation of PKC, despite unambiguous tumor promoting function in certain contexts, can be beneficial for the treatment of Fli-1-induced leukemia." (PMID 28052010, 2017). "Moreover, in a mouse model of leukemia initiated by Fli-1 activation, the PKCA compounds exhibited strong anti-cancer activity, which was accompanied by increased presence of CD41/CD61 positive megakaryocytic cells in leukemic spleens." (PMID 28052010, 2017). "Therefore, we analysed primary and secondary Fli-1 leukaemias and MigR1 controls for Bcl-2, Bcl-xL and Mcl-1 mRNA expression by Q-PCR." (PMID 23667468, 2013). "Thus, both inhibition and activation of Fli-1 appear to have therapeutic applications for leukemia." (PMID 28052010, 2017). "To determine whether our PKCA compounds can suppress leukemia progression in vivo, we used a mouse model of erythroleukemias induced by F-MuLV, in which insertional activation of Fli-1 occurs as early as 40 days post viral injection, is the initial event during leukemogenesis." (PMID 28052010, 2017). "As FLI1 also regulates HDC, some of its anti-leukemia activity is likely mediated through HDC suppression." (PMID 39769192, 2024). "Deregulated expression of multiple ETS factors like ERG, FLI1 and SPI1 contribute to the genesis of leukemia and impact the survival outcome in leukemia patients." (PMID 37895265, 2023). "Lovastatin had marginal effect on Fli-1 expression on murine erythroleukemia cell line CB3 induced by this retrovirus, suggesting that lovastatin inhibits leukemia progression independently of Fli-1." (PMID 37016335, 2023). "In support of this association, Tet‐induced depletion of OTUD7A in kidney cancer (ACHN) and leukemia (Jurkat and CUTLL1) cells reduced levels of endogenous FLI1 accompanied by reduced cell proliferation." (PMID 34060252, 2021). "Consistently with the high homology between ERG and FLI1, transplantation of these MN1–FLI1-transduced cells was sufficient for the development of murine leukemia presenting clear features of AMKL." (PMID 31681706, 2019). "Therefore, tackling the interplay between FLI-1 and the LDB1 complex in human primary cells will definitely validate its role in leukemia and megakaryopoiesis." (PMID 33733070, 2021). "AM extracts contain additional compounds with known anti-leukemia activity, independent of FLI1." (PMID 39769192, 2024). "As Kyn activity was recently reported to be induced by FLI1 in nasopharyngeal carcinoma, this process was not affected by the FLI1 inhibitor Ba, indicating different regulation of the inflammatory process by this transcription factor in leukemia." (PMID 39769192, 2024). "However AR151 did not have leukemia and did have a Fli1 glioma insertion." (PMID 25423036, 2014).
prostate carcinoma (36 papers, 2011 to 2025). A carcinoma that arises from epithelial cells of the prostate gland. "Based on genomic profiles, prostate cancer can be divided into seven molecular subtypes which bear distinct oncogenic drivers including fusions with ETS family members (ERG, ETV1, ETV4, and FLI1) and mutations in SPOP, FOXA1, and IDH1." (PMID 33273988, 2020). "A study of a cohort of 333 primary prostate carcinomas showed that 74% of these tumors fell into one of seven subtypes of a molecular taxonomy defined by specific gene fusions (ERG,ETV1/4 and FLI1) or mutations (SPOP,FOXA1 and IDH1)." (PMID 33058520, 2020). "Our study shows that targeting Fli-1 can be such an alternative strategy to control the proliferation and metastasis of prostate cancer." (PMID 32210104, 2020). "An earlier study of a cohort of 333 primary prostate carcinomas showed that 74% of these tumors fell into one of seven subtypes of a molecular taxonomy defined by specific gene fusions (ERG, ETV1/4 and FLI1) or mutations (SPOP, FOXA1 and IDH1)." (PMID 33058520, 2020). "In this study, we explored the activity and molecular mechanism underlying the action of C10, an Fli-1 agonist, on the growth and metastatic capability of PC3 prostate cancer cells." (PMID 32210104, 2020). "The discovery and functional validation of recurrent gene fusions of 5 Ets factor genes (ETV1, ETV4, ETV5, ERG, Fli1) in prostate cancer highlights the relevance of Ets transcription factors as oncogenes in prostate cancer." (PMID 26885618, 2016). "FLI1 fusions have also been found in prostate cancer and abnormal FLI1 expression in AML patients correlates with poor prognosis." (PMID 24827933, 2014). "As predicted, V5-tagged EWS/FLI1 expressed in PC3 prostate cancer cells bound to purified ERG." (PMID 37956771, 2023). "Based on this strategy, we hypothesized that C10 might act as an agonist for Fli-1 expression in prostate cancer cells, which was opposite to the role of Fli-1 in other cancers." (PMID 32210104, 2020). "In an analysis of 333 individual prostate cancer exomes, TCGA identified seven subtypes defined either by gene fusions involving the ETS family (59% of cases), specifically ERG, ETV1, ETV4, or FLI1, or recurrent mutations (15% of cases) in SPOP, FOXA1, or IDH1." (PMID 28423598, 2017). "Using the TaqMan Low Density Array (TLDA) technology, we evaluated the expression of the five ETS genes known to be involved in genomic rearrangements in PCa (ERG, ETV1, ETV4, ETV5 and FLI1) in a panel of cell lines representing various subtypes of prostate cancer." (PMID 25595908, 2015). "PXN expression was relatively high in ERG1- and FLI1-fusion-positive prostate cancers and SPOP-mutant prostate cancer, but it was relatively low in ETV1- and ETV4-fusion-positive prostate cancers." (PMID 36289913, 2022). "The SLFN11 promoter contains several ETS binding sites and functions as an ETS factor response gene, with ETS transcription factors FLI1 and ETS1 having proposed roles in regulating SLFN11 expression in colon, breast, and prostate cancers." (PMID 28212573, 2017). "The most prevalent gene fusion is the TMPRSS2-ERG, present in nearly half of all human prostate cancers, followed by rearrangements involving the ETV1, ETV4, ETV5 and FLI1 genes, often with promoter fusion partners other than TMPRSS2." (PMID 25595908, 2015). "Since ERG and ETV1 belong to the same class of ETS factors as FLI1, we tested the ability of YK-4-279 to inhibit biological functions of ERG and ETV1 proteins in prostate cancer." (PMID 21559405, 2011). "The DNA binding domain of ERG shares 98% homology with that of FLI1 and our own unpublished results suggest that there is significant overlap between EWS-FLI1 target genes in ESFT and ERG in prostate cancer cells." (PMID 22135504, 2011).
prostate carcinoma (continued). "About 50–70% of prostate carcinomas harbor common chromosomal rearrangements fusing one of the ETS transcription family genes (ERG, ETV1, ETV4 or FLI1) with androgen-regulated genes, most commonly TMPRSS2, leading to disruption of androgen receptor signaling via activation of EZH253." (PMID 32873863, 2020). "Consistently, the radial repositioning patterns of FLI1, MMP9 and MMP2 also do not correlate with the risk/aggressiveness of prostate cancer." (PMID 31681438, 2019). "To validate that the effect on EWS/FLI1 target genes by the compound is due to the presence of EWS/FLI1, we performed the same assays in prostate cancer cells lacking the fusion protein." (PMID 26336820, 2015). "As EWS–FLI1 includes the FLI1 Ets portion and some upstream regions, both RHA and YK-4-279 potentially directly bind the Ets domain, particularly as YK-4-279 also inhibits ERG and ETV1-mediated invasion in prostate cancer." (PMID 24450640, 2014).
alveolar rhabdomyosarcoma (31 papers, 1999 to 2025). A rapidly growing malignant mesenchymal neoplasm. "The first data demonstrating a relationship between CCK expression and EWS/FLI1 came from studies performed in heterologous systems: ectopic expression of EWS/FLI1 in the RD rhabdomyosarcoma cell line and in HeLa cells upregulated CCK mRNA levels." (PMID 26258070, 2015). "In addition, FLI-1 positivity was also helpful even though its expression is noted in lymphomas, rhabdomyosarcomas and synovial sarcomas." (PMID 20233457, 2010).
melanoma (24 papers, 2016 to 2025). A malignant, usually aggressive tumor composed of atypical, neoplastic melanocytes. "In a previous study of malignant melanoma, Fli-1 expression was found to be associated with a higher proliferation rate of neoplastic cells." (PMID 28418872, 2017). "A total of 12 TFs were identified, among which the expression of STAT1, IRF1, and FLI1 in C4 Melanoma CORO1A was higher than that of other subtypes." (PMID 37435067, 2023). "In order to further investigate the relationship between gene expression levels of STAT1, IRF1, and FLI1 and survival probability in melanoma patients, Kaplan-Meier survival plots of high and low gene groups for these TFs were utilized." (PMID 37435067, 2023). "Strong expression of FLI-1 has been reported only in seven cases of melanoma that displayed variable expression of melanocytic markers." (PMID 34449584, 2021). "Other studies identified Fli-1 overexpression as a biomarker of certain cancers including melanoma, ovarian cancer, endometrial cancer, breast cancer, and nasopharyngeal carcinoma (NPC)." (PMID 28418872, 2017). "For the first time, we show that CD13/ANPEP and FLI1 overexpression can mediate resistance to BRAFi in melanoma cells." (PMID 29048432, 2017). "This is the first report presenting CD13/ANPEP and FLI1 as important mediators of resistance to BRAF inhibition with potential as drug targets in BRAFi refractory melanoma." (PMID 29048432, 2017). "FLI-1 is also expressed at high levels in F-MuLV-induced erythroleukemias, malignant melanoma, small cell carcinomas of the lung and adenocarcinomas." (PMID 27304058, 2016). "CD8+ T cells in the CRATERs contacted either fli1+ vessels (area 1) or melanoma cells (area 2)." (PMID 41109214, 2025). "We also visualized the expression of FLI1 in different stages of melanoma." (PMID 33971970, 2021). "Strong and diffuse expression of FLI-1 in melanoma in the setting of metastasis with unusual morphology could be deceiving." (PMID 34449584, 2021). "These pathways include lipid biosynthesis and regulation (e.g., Steroid hormone biosynthesis, Steroid Biosynthesis, Statin pathway, cytochrome P450 activity), as well as proto‐oncogenic genes and cancer (e.g., {CTNNB1, 130} [Static Module], {FLI1, 10} [Static Module], Melanoma [KEGG])." (PMID 29773677, 2018). "In addition, the protective factors of skin melanoma, STAT1, IRF1, and FLI1, may modulate melanoma cell responses to NK or T cells." (PMID 37435067, 2023). "Importantly, we discovered that STAT1, IRF1, and FLI1, the protective factors of melanoma, may regulate the response of melanoma cells to NK and T cells by modulating the expression of positive NK and T cell regulation activation-related genes." (PMID 37435067, 2023). "In melanoma, several ETS TFs, including FLI1, SPI1, ELF4, ETV7, SPIB, and SPIC, are expressed at higher levels in Cluster A patients, whereas ETV5, ETV4, ELK1, ERF, and ETV2 showed increased expression in Cluster B patients." (PMID 41502516, 2025). "The 12 TFs that were inferred to regulate NK and T cells activation in these modules are shown as follows: Module M1 contained the regulators IRF1, STAT1, SPI1, FLI1, IRF7, and E2F1, which are essential regulators for C4 Melanoma CORO1A." (PMID 37435067, 2023). "More investigation on EndMT in tumour microenvironment revealed the role of two transcription factors in EndMT in melanoma, ERG, and FLI1." (PMID 36077754, 2022). "Through protein expression scanning by the Human Protein Atlas, overexpression of FLI1, CD28, CD80, and IL21R was discovered in melanoma." (PMID 33971970, 2021). "In contrast, within tumors formed after subcutaneous injection of B16F10 melanoma cells, some ECs showed reduced expression of ERG and FLI1." (PMID 30500808, 2018).
melanoma (continued). "Melanoma tumours also display reduced expression of ERG and FLI1 in tumour endothelial cells." (PMID 36077754, 2022).
bone cancer (23 papers, 2003 to 2025). A primary or metastatic malignant neoplasm affecting the bone or articular cartilage. "These four gene-cancer pairs were EWSR1 (26.3% vs. 13.0%) and FLI1 in bone cancer (23.2% vs. 9.6%), BRAF in glioma (3.6% vs. 0.4%), and TEF3 in renal cell carcinoma (8.5% vs. 1.7%)." (PMID 36433963, 2022). "The chimeric fusion gene EWS/Fli1 is detected in the majority of ES, the second most common malignant bone tumor of childhood." (PMID 29147265, 2011).